CD80 (CD80 molecule)
Diseases named in the same sentence as CD80 in open-access papers (continued):
Sharing a sentence is not in itself a finding about the gene and the disease.
tumor (continued). "Specifically, we detected an increase of CD11b+CD80+ (M1‐like) macrophages together with a decrease of CD11b+CD206+ (M2‐like) macrophages in the tumour tissue of the shc‐Myc group treated with PD‐L1 inhibitor and Salirasib compared with the control group, resulting in an elevated CD80/CD206 ratio." (PMID 41020311, 2025). "Notably, the Bead+ monocytic cells recruited to irradiated tumors upregulate CD80 to a similar degree to the Bead− cells (Fig. 4Biii-iv), demonstrating that recruited cells are induced to upregulate CD80 once in the tumor environment." (PMID 41417245, 2025). "Hence, we assessed the tumor cell expression of four distinct immune checkpoint ligands; PD-L1, CD80, GAL-9, and PVR, which interact with the clinically relevant receptors PD-1, CTLA-4, TIM3, and TIGIT on T cells." (PMID 40108668, 2025). "Thus, the interaction between PD-L1 on T cells and CD80 on tumor cells or APCs appears to have immunosuppressive effects against T cells." (PMID 41425548, 2025). "In addition, MAP1LC3C correlates with tumor-cell associated CD80 and CD86, cell costimulatory surface proteins that are primarily expressed on antigen-presenting cells (APCs) and tumor cells." (PMID 39928678, 2025). "Immunohistochemical staining confirmed increased infiltration of CD4 + T cells, CD8 + T cells, monocyte chemoattractant protein-1, CD80-, and iNOS- positive macrophages into the tumor microenvironment of this group, with a marked reduction in CD206-positive macrophages." (PMID 40836337, 2025). "Additionally, we observed significant enrichment of signaling pathway interactions, including CD99, IFN-II, and CD80, in tumor-reactive (TR) CD8 + T cells." (PMID 40855305, 2025). "Last, there was an upregulation of surface CD80 and CD86 expression in the Ly6C+MHC-II+ macrophages, suggesting that anti-PDL-L1 therapy attenuated the loss of inflammatory gene expression following tumour infiltration." (PMID 40523200, 2025). "Finally, analyzing the interactions between myeloid cells and tumor cells, we found that high expression of CD80 and CD86 in dendritic cells promoted immune responses or inhibited immune evasion." (PMID 40104502, 2025). "Co-receptors CD80 (B7-1) and CD86 (B7-2) that are expressed on antigen-presenting cells (APCs) are also receptors of AdV3, allowing for the possibility of AdV3s to infect APCs and provide the tumor-associated antigens directly (if modified to do so)." (PMID 39309012, 2024). "Applying pan-cancer TME signatures, non-NE TME was marked by immune infiltration including natural killer (NK) cells, B cells, and M1 tumor-associated macrophages (TAM-M1) and upregulation of immune co-activators (CD40LG, CD80) compared with hybrid-NE and NE TME." (PMID 38897168, 2024). "The preclinical study indicated that JS007 could effectively block the CTLA-4/CD80 immune inhibitory signaling pathway, promote T-cell activation and proliferation, thereby boost the immune response to eliminate tumor cells." (PMID 39354625, 2024). "The enhanced cross-dressing with live tumor-derived MHCI may be ascribed to up-regulation of CD80/86 expression." (PMID 38680663, 2024). "PD-1/CD80+ I-sEVs also induce downregulation of adhesion- and antigen presentation-related molecules on tumour cells and impaired immune cell infiltration, thereby converting tumours to an immunologically cold phenotype." (PMID 38719909, 2024). "Finally, higher levels of mature DCs (CD11c+CD80+CD86+) in the tumor draining LNs and CD8+ cytotoxic T cells in untreated distant tumors were recorded." (PMID 38803496, 2024). "However, the tumor microenvironment poses challenges, as cancer cells often exhibit an elevated expression of co-inhibitory protein ligands, including CD80/86 and programmed death-ligand 1 (PD-L1)." (PMID 38248769, 2024).
tumor (continued). "In the present study, while CD86 and PD-L1 were expressed at constant levels throughout tumor growth and regression phases, the level of CD80 positive cells was shown to decline during the latter pointing to a CD80 mediated effect on tumor immune evasion in CCH." (PMID 38962703, 2024). "Ipilimumab is a monoclonal antibody against cytotoxic T lymphocyte antigen-4 (CTLA-4), which is known to inhibit binding of CD80 and CD86 molecules on antigen-presenting cells, thereby causing proliferation and activation of T cells and promoting presentation of tumor antigen." (PMID 38187173, 2024). "Additionally, PD-L1 on tumor cells also interacts with CD80 on activated T cells, decreasing the activation of effector T cells and even inducing apoptosis of activated T cells." (PMID 38762484, 2024). "(III) Signaling of PD-L1 within cancer cells may prevent the apoptosis of tumor cells themselves, and the interaction of PD-L1 with CD80 can suppress the immune response, etc." (PMID 38762484, 2024). "The role played by CD80 is similar to that of PD-1-blocking scFv, and we guess that blocking the interaction between PD-L1 and PD-1 by CD80 may have better anti-tumor efficacy than PD-1-blocking scFv." (PMID 39575257, 2024). "Additionally, it was found that the expression level of CD80 on CD11c+CD103+ DCs in the tumours of mice treated with PAK4 inhibitors was significantly higher." (PMID 38890401, 2024). "We can speculate that the activation of CD28 is so crucial that CD80 as its ligand may bring more possibilities in tumor treatment." (PMID 39575257, 2024). "Ceralasertib treatment caused increase in the percentage of tumor CD11c+MHC II+ dendritic cells (DCs) and marked up-regulation of the expression of molecules associated with DC activation: MHC class II (IAb), MHC class I (H2Kb), CD40, and CD80." (PMID 38402224, 2024). "This may be due to chemotherapy activating endogenous anti-tumor immune responses, leading to increased expression of co-stimulatory molecules CD80 and CD86 and downregulation of PD-L1, inducing immunogenic tumor cell death." (PMID 39072331, 2024). "Taken together, these results together suggest that PD-1/CD80 carried on aT-sEVs might transligate and internalise tumour cell surface PD-L1 to enhance its secretion via sEVs." (PMID 38719909, 2024). "In addition, the CD80/GM-CSF modified fusion vaccine showed more significant anti-tumor effects and a stronger ability to stimulate immune responses in vitro than the vaccine without specific modification." (PMID 39575257, 2024). "Positive labeling with the anti-CD80 antibody in tumor cells in dogs with hematopoietic neoplasms." (PMID 39224452, 2024). "Furthermore, the CTLA-4/CD80, CD86 axis established between immune cells and tumor cells has been implicated in attenuating anti-tumoral immune responses in the tumor microenvironment." (PMID 38893120, 2024). "In vivo experiments demonstrated that injection of colon cancer-derived exosomes could inhibit the activity and expansion of tumour-specific T cells and DCs, reduce the expression of CD28 and CD80/86, and promote tumour growth." (PMID 38302430, 2024). "It has been shown that the CD80 surface molecule preferentially engages with the inhibitory protein cytotoxic T-lymphocyte associated protein 4 (CTLA4) on T-lymphocytes, leading to immune exhaustion and tumor growth." (PMID 38891044, 2024). "One mechanism, by which the tumor cells escape the host’s immune response is the hijacking of immune-checkpoints, like programmed cell death ligand 1 (PD-L1), CD80, CD86 and their respective receptors, programmed death receptor 1 (PD-1) and cytotoxic T-cells associated protein 4 (CTLA-4)." (PMID 38962703, 2024). "Unlike FPT155, ALPN-202 is a mutated CD80-Fc fusion protein designed to overcome checkpoint inhibitor resistance by enhancing CD28 costimulation in the tumor microenvironment while inhibiting PD-L1 and CTLA-4." (PMID 39575257, 2024).
tumor (continued). "CTLA-4 blockade with ipilimumab and other Abs has been reported to impede tumors through various mechanisms, primarily by favoring CD28 binding to CD80/86, especially in tumor-draining lymph nodes where APCs cross-present tumor antigens to activate tumor-reactive T-cells." (PMID 39684559, 2024). "Moreover, combination therapy upregulates antigen-presenting factors, such as MHC I/II and the coactivators CD80/86 in macrophages, promoting adaptive anti-tumor immune responses." (PMID 39135069, 2024). "As early as 1997, studies showed that IL-2(+) and CD80(+) tumor vaccines could protect and prolong the survival time of a higher proportion of sarcoma-bearing mice compared with IL-2(+) tumor vaccines." (PMID 39575257, 2024). "It is now clear that further improvements in rates and durability of responses may require combining CD80 with other therapies that stimulate a proinflammatory immune response within the tumor microenvironment." (PMID 39575257, 2024). "It has been found that low expression of CD80 in tumor stem cells may inhibit the activation of the CD28 molecule on T cells in glioblastoma." (PMID 39575257, 2024). "CTLA-4 inhibition by monoclonal antibodies may induce tumor rejection through direct blockade of CTLA-4 competition for CD-80 (B7-1) and CD-86 (B7-2) ligands, which enhances CD28 co-stimulation." (PMID 39091917, 2024). "It simultaneously blocks CTLA-4 with CD80/85 and PD-L1 with programmed cell death-1 (PD-1) to inhibit immunosuppressive effects, which restores T-cell effector immune response to tumor and deletes Treg cells (suppress tumor immunity) in tumor microenvironment." (PMID 38310192, 2024). "By applying CD80 antibodies, fusion proteins, or combining with CAR-T or other therapies, CD80 may offer a new direction for tumor immunotherapy." (PMID 39575257, 2024). "Tumor segments in Type 2 OC (HGSC) were shown to have stronger infiltration of immune cells, including CD3, CD4, CD11c, CD163, CD56 and CD80, suggesting that both pro- and anti-inflammatory immune phenotypes are elevated inside the tumor nests compared to Type 1 OC." (PMID 39026018, 2024). "Conversely, the upregulation of CD80 induces T-cell activation and enhances tumor rejection." (PMID 38590525, 2024). "Immunofluorescence analysis of allograft tumor tissues revealed that BPTES reduced the protein levels of CD80, CD204, hypusinated eIF5A, and HIF-1α, indicating that inhibition of HCC growth can be achieved by targeting eIF5A hypusination in TAMs via regulation of glutamine metabolism." (PMID 38689086, 2024). "The important role of CD80 in T cell activation makes it an option for tumor vaccine adjuvant." (PMID 39575257, 2024). "A potential explanation for these opposing functions of PD-L1 expression for T cell activity has recently been proposed by Bromberg and coworkers who showed that exclusive in-cis-binding of PD-L1 promotes anti-tumor immunity, while engagement of CD80 and PD-L1 in-trans inhibits immune-responses." (PMID 37187729, 2023). "In addition, the tumor DT2 * enhancement positively correlated with the quantity of CD80 and inducible nitric oxide synthase (iNOS)-positive TAM on the histology and the tumor size on post-treatment scans." (PMID 36961012, 2023). "Therefore, with the TCGA database, we separately calculated the differential expression of CD80 in LUAD tumor tissues and paracancerous tissues." (PMID 36892747, 2023). "Notably, TAMs had putative interactions with tumor‐infiltrating T cells through CD80/CD86‐CTLA4, PDL1/PDL2‐PD1, and LGALS9‐HAVCR2, suggesting their immunosuppressive capability on T cells." (PMID 37949673, 2023). "Utilizing ICIs to block inhibitory PD-1/PD-L1 and CTLA-4/CD80/86 signaling pathways improves the generation of efficient immune responses against cancer cells, revitalizes tumor antigen recognition, and ultimately leads to tumor death." (PMID 37038154, 2023).
tumor (continued). "In addition, the supernatant of hypofractionated irradiated tumor cells elevated the percentage of migrating DCs and raised the activation markers CD80 and CD86 expression." (PMID 37833255, 2023). "Rhythmic trafficking of dendritic cells to the tumour draining lymph node governs a circadian response of tumour-antigen-specific CD8+ T cells that is dependent on the circadian expression of the co-stimulatory molecule CD80." (PMID 36470303, 2023). "Furthermore, the tumours that have normal expression of MHC molecules often lack co-stimulatory molecules such as CD80 or CD86, which abrogates the activation of T lymphocytes." (PMID 37631324, 2023). "Next, we used the CIBERSORT algorithm to analyze whether CD80 expression could influence the distribution of infiltrating immune cells in tumor tissues." (PMID 36892747, 2023). "Interestingly, unlike in the case of macrophages, the combination CpG-STAT3ASO/anti-PD-1 treatment but not CpG-STAT3ASO or anti-PD-1 alone led to a significant recruitment of activated (MHC-IIHI and CD86+ or CD80+) DCs into tumor-draining lymph nodes." (PMID 38259453, 2023). "Finally, the results of the current study demonstrated that CD80, the surface marker of M1, can regulate the tumor microenvironment and potentially be a prognostic indicator." (PMID 37124547, 2023). "However, RT and the combined treatment were able to polarize macrophages into a pro-inflammatory and anti-tumor phenotype characterized by the upregulation of the activation marker CD80." (PMID 37907934, 2023). "Proinflammatory M1‐like markers, such as CD80, TNFα, CXCL10, tend to be associated with an antitumor immune response, while macrophages expressing other proinflammatory cytokines (IL‐1β, IL‐6) can mediate tumor cell migration and cancer progression." (PMID 38037545, 2023). "Additionally, the remaining macrophages detected in the tumor from the VSSP-treated mice exhibited an M1 phenotype characterized by an increased expression of CD80, IL-12 and TNFα." (PMID 37055829, 2023). "Flow cytometry of the tumor immune microenvironment revealed a decreased expression of the M2 marker arginase in tumor-associated macrophages but an unchanged expression of M1 markers INOS, CD80 and MHC I and an increase in M1 marker CD64." (PMID 37835464, 2023). "Therefore, the maturation of DCs (CD11c+CD80+CD86+) in tumor draining lymph nodes was analyzed by flow cytometry after different treatment." (PMID 37051250, 2023). "Similarly, multiple pathways implicated in PKD (e.g., IFN-γ/JAK-STAT, TNF-α, NF-κB, PI3K, and HIF-1) drive PD-L1 and CD80/CD86 expression on tumor cells." (PMID 37345660, 2023). "The results demonstrated that mPEG-Pep-IDOi/ICG could enhance killing efficacy through CCK-8 assay, induce ICD of tumor cells and upregulate CD80 and CD86, sustaining the DC maturation." (PMID 37238966, 2023). "Upregulation of CD80 may interact with cytotoxic T lymphocyte antigen 4 (CTLA4) to promote tumor progression and provide a potential target for biological antitumor therapy." (PMID 36892747, 2023). "Our previous studies also showed that upregulating CD80 expression on tumor cells or combining with bispecific antibody could enhance T cell function of lysing tumor cell." (PMID 37488603, 2023). "Cis-PD-L1 interacts with CD80 to obtain an optimal T-cell response to destroy the tumor." (PMID 37143720, 2023). "Regarding in vivo tests, TLipIT/NEs under laser irradiation had the best local tumor suppression, the CD80+ and CD86+ mature DCs frequency was ≈33%, significantly higher than the ≈ 16% measured without NIR irradiation, and the ≈11% registered when PBS only was used." (PMID 37238966, 2023). "Finally, antibody treatment against CD80 abrogated the differences in tumour volume after time-of-day-dependent engraftment, demonstrating the functional relevance of CD80 in vivo in driving differences in tumour size." (PMID 36470303, 2023).
tumor (continued). "Simultaneously, it stimulated DCs and macrophages to express more CD80/86 co-stimulatory molecules and produce more interleukin-12 (IL-12), thus countering the immunosuppressive environment around tumor cells and triggering a range of anti-tumor immune responses." (PMID 38274735, 2023). "The engagement of CTLA-4 with its ligand (CD80/86) may also result in immunosuppression against developing tumor cells, by mediating immune evasion and escape mechanism of tumor cells." (PMID 37038154, 2023). "Further, CD80 co‐expression inhibits the expression of PDL1 on the tumor cell surface." (PMID 37476068, 2023). "Interestingly, cells of different tumor types seem to evade antitumor immunity via disparate expression of CD80." (PMID 36892747, 2023). "In addition to blocking the PD-1-PD-L1 pathway, PD-L1 inhibitors block the ability of PD-L1 on the tumour cell surface to bind CD80 on the T cell surface." (PMID 36016159, 2022). "Higher CD80 expression was also detected when GILT levels were increased for the J3.DR4.GILT tumor." (PMID 35162988, 2022). "Moreover, B cells in TLSs can function as antigen-presenting cells; they highly express the co-stimulatory molecules CD86 and CD80 and facilitate tumor antigen-specific T-cell responses, including CD8+ TIL and CD4+ TIL responses." (PMID 35663939, 2022). "The content of mature dendritic cells (CD80+CD83+) in the tumor node was assessed." (PMID 35693632, 2022). "Enhanced CD80 expression on DCs induced by tumor cell coculture was significantly attenuated, but not completely reversed, in DCs cocultured with Smad4 re‐expressed tumor cells." (PMID 35064757, 2022). "Of note, improved antigen presentation and increased frequency of tumor associated DCs with high expression of CD40, CD80, and CD86 co-stimulatory molecules have been described in response to olaparib, together with enhanced transition of CD8+ T cells to the tumor site." (PMID 36428727, 2022). "Cytotoxic T lymphocyte-associated antigen-4 (CTLA-4), also known as CD152, is a membrane protein expressed on CD4+ and CD8+ T cells that is involved in the downregulation of T cell immune response at the tumor site upon interaction with CD80/B7.1 and CD86/B7.2 on APC." (PMID 35625811, 2022). "As the binding of PD-L1 to PD-1 or CD-80 inhibits the activation of T-lymphocytes, this blockade impairs the tumor immune system evasion by allowing T-cell responses to occur, thus enhancing anti-tumor activity." (PMID 35267561, 2022). "The use of a monotherapy against either PD-1/PD-L1 or CTLA-4/CD80 may apply a positive selection pressure to a tumor, resulting in the outgrowth of clones that are able to modulate other immune checkpoints." (PMID 36497220, 2022). "Additionally, the expression of tumor-associated antigens such as MHC class I and class II molecules, as well as costimulatory CD80 and CD40, is also augmented by HDAC inhibition, so these tumors get more susceptible for immunotherapy." (PMID 35055045, 2022). "In our case, reduced expression of CD80 on tumor cells by H89 may reduce the tumor-mediated exhaustion of both CD4+ and CD8+ TLs." (PMID 35572581, 2022). "Furthermore, when we analyzed the expression of the CD80 on tumor-migratory (Kaede-red) DCs, we noted a significant increase in the frequency and intensity of this maturation marker on both CD103+ and CD11b+ cDCs." (PMID 35487695, 2022). "CD80 has also been reported to promote the memory response in cytotoxic T lymphocytes (CTLs), which suggests that the CD80 expression on the tumor is involved in antitumor CTL effector function." (PMID 35814211, 2022). "Furthermore, the 19z1-CD80-41BBL configuration, in which CAR coupled with both CD80 and 41BBL simultaneously, was the least effective, expanding steadily but exerting inferior tumor control." (PMID 36123710, 2022). "Moreover, CD80+ and CD86+ dendritic cells present in peritumoral tissues of NSCLC patients were associated with an immature phenotype that favors tumor immune escape." (PMID 35688943, 2022).